VEGFC (vascular endothelial growth factor C)
Diseases named in the same sentence as VEGFC in open-access papers (continued):
Sharing a sentence is not in itself a finding about the gene and the disease.
ovarian carcinoma (47 papers, 2003 to 2025). A malignant neoplasm originating from the surface ovarian epithelium. "Consistently, VEGFC promoter methylation was reported to be associated with progression‐free survival in ovarian cancer." (PMID 31069961, 2019). "Overall, these observations suggested that the expression of the adhesion-related genes ITGA2 and VEGFC may be associated with the increased adhesiveness of M-Met5A cells toward ovarian cancer cells." (PMID 36766725, 2023). "Several molecular factors have been implicated in ovarian cancer lymph node metastasis, including USP7, FAK, and the VEGFC-VEGFR3 signaling axis, all of which are associated with an increased incidence of lymphatic metastasis in ovarian cancer patients." (PMID 40109727, 2025). "Taken together, these data indicated that the JNK and Akt pathways regulate the mRNA expression of ITGA2 and VEGFC, thereby modulating the adhesiveness of M-Met5A cells toward ovarian cancer cells." (PMID 36766725, 2023). "Here, we found that the mesothelial expression of ITGA2 and VEGFC was induced by macrophages and enhanced the adhesion of ovarian cancer cells to mesothelial cells." (PMID 36766725, 2023). "Inhibition of the JNK and Akt signaling pathways suppressed ITGA2 and VEGFC expression in M-Met5A cells as well as ovarian cancer-mesothelial cell adhesion." (PMID 36766725, 2023). "In this study, we demonstrated that CCL2 and CCL5 derived from macrophages induced mesothelial expression of the adhesion-related genes ITGA2 and VEGFC to increase the adhesion of ovarian cancer cells." (PMID 36766725, 2023). "Knockdown of ITGA2 and VEGFC in M-Met5A cells significantly inhibited the adhesion of ovarian cancer cells." (PMID 36766725, 2023). "Previous studies have shown that ITGA2 and VEGFC play important roles in the invasion and angiogenesis of various cancers, including gastric and ovarian cancer." (PMID 36766725, 2023). "Previous studies reported that BACH1 induces angiogenesis and lymphangiogenesis by regulating the transcription of VEGFC to promote the expansion and aggressiveness of ovarian carcinoma." (PMID 33932125, 2021). "In CAOV-3 cells, CXCL12 and its receptor CXCR4 stimulated the secretion of integrin β-1 and vascular endothelial growth factor-C (VEGF-C), indicating the involvement of this receptor in the stimulation of tumor vasculature in ovarian cancer." (PMID 31703453, 2019). "We next performed luciferase reporter assays to confirm the NF-kB binding site within the VEGFC promoter region in ovarian cancer cells." (PMID 29717026, 2018). "Consistently, Huang and Sui showed that the positive rate of MMP-2, vascular endothelial growth factor C (VEGF-C) and E-cadherin in ovarian cancer is higher than that in benign and borderline ovarian tumors." (PMID 28538838, 2017). "Inhibition of vascular endothelial growth factor in ovarian cancer is clinically relevant and the high relative expression of VEGFC implicates this pathway in PH003 growth." (PMID 25962155, 2015). "In the present study we analyzed the predictive potential of vascular endothelial growth factor C (VEGF-C) to identify ovarian cancer patients that might benefit from an antiangiogenic therapy." (PMID 35687576, 2022). "Taken together, these data indicated that CCL2 and CCL5 secreted by macrophages can increase the expression of adhesion-related genes ITGA2 and VEGFC via the JNK and Akt pathways in Met5A cells, resulting in enhanced ovarian cancer-mesothelial cell adhesion." (PMID 36766725, 2023). "ITGA2, VEGFC, and their regulatory pathways, JNK and Akt, play critical roles in increasing the adhesion of macrophage-stimulated mesothelial cells to ovarian cancer cells." (PMID 36766725, 2023). "In ovarian cancer cells, CXCL12 and its receptor CXCR4 increased the production of integrin-1β and vascular endothelial growth factor-C (VEGF-C), activating tumor vasculature in ovarian cancer." (PMID 34912809, 2021).
ovarian carcinoma (continued). "To determine whether ITGA2 and VEGFC are involved in the enhanced adhesiveness of M-Met5A cells, we further investigated the effect of ITGA2 and VEGFC knockdown on ovarian cancer mesothelial cell adhesion." (PMID 36766725, 2023). "Similarly, treatment with fucoidan repressed the mRNA expression of angiogenesis related genes including VEGFA, VEGFB, VEGFC, VEGFD, FLT-1, FLT-4, and KDR in the ovarian cancer cells." (PMID 31936539, 2020).
prostate carcinoma (45 papers, 1999 to 2026). A carcinoma that arises from epithelial cells of the prostate gland. "Higher expression of VEGFC occurs after NKX3.1 loss in prostate cancer and is correlated with lymph node metastasis of prostate cancer." (PMID 20070897, 2010). "For example, PNI-positive prostate cancer cells overexpress vascular endothelial growth factor C (VEGFC), promoting lymphatic metastasis of prostate cancer." (PMID 40421086, 2025). "Vascular endothelial growth factor-C protects prostate cancer cells from oxidative stress by the activation of mammalian target of rapamycin complex-2 and AKT-1." (PMID 37469162, 2024). "Expression of vascular endothelial growth factor C (VEGF-C) and VEGF receptor-3 in human prostate cancer is associated with regional lymph node metastasis." (PMID 37469162, 2024). "Meanwhile, calpain-2 was proven to contribute to the methylation of CRMP4′s promoter, repressing its transcription, thereby promoting the metastasis of prostate cancer by enhancing expression of vascular endothelial growth factor C." (PMID 35625600, 2022). "To explore the molecular mechanisms governing VEGFC expression, we searched for genes that co-express with VEGFC in human prostate cancer datasets." (PMID 32132179, 2020). "Since the NKX3-1 gene region is frequently lost in prostate cancer and this leads to increase vascular endothelial growth factor-C (VEGF-C) expression, NKX3-1 is known as a tumor suppressor gene." (PMID 28264478, 2017). "In particular, ANGPT2, CYR61 and VEGFC are involved in angiogenesis and are up-regulated in prostate cancer." (PMID 22328933, 2012). "Although not common, the VEGFC/KLK3 SNP–SNP interaction pair rs174776/rs3775202 was highly significantly associated with prostate cancer aggressiveness." (PMID 34948344, 2021). "Recently, a novel decoy function of s9NRP2 in sequestering VEGFC and inhibiting the oncogenic VEGFC/NRP2 signaling has been reported in prostate cancer cells where it significantly reduced the formation of prostatospheres." (PMID 29067024, 2017). "Additionally, in prostate cancer cells, FOXO1 has been shown to promote the upregulation of VEGFC." (PMID 38899748, 2024).
non-small cell lung carcinoma (34 papers, 2001 to 2025). A group of at least three distinct histological types of lung cancer, including non-small cell squamous cell carcinoma, adenocarcinoma, and large cell carcinoma. "The aim of this study is to investigate the expressions and their significances of vascular endothelial growth factor-C (VEGF-C) mRNA and epidermal growth factor receptor (EGFR) mRNA in non-small cell lung cancer (NSCLC) tissues and lymph node tissues." (PMID 21159248, 2010).
colon carcinoma (33 papers, 2007 to 2023). "VEGFC is one of the main secretory proteins associated with various steps of colon cancer progression." (PMID 37509740, 2023). "For example, overexpression of miRNA182-5p in a colon cancer model inhibited colon cancer tumorigenesis, angiogenesis, and lymphangiogenesis by directly down regulating vascular endothelial growth factor C." (PMID 35711428, 2022). "For instance, miR-182-5p restrains the lymphangiogenesis and tumorigenesis in colon cancer by targeting vascular endothelial growth factor-C (VEGF-C)." (PMID 35509687, 2022). "For the detailed mechanism study, we used in vivo and in vitro models to investigate the process by which BRG1 promotes VEGFC transcription, then induced the lymphangiogenesis in colon cancer cell lines and xenograft tumors." (PMID 27145366, 2016). "We found that downregulation of BRG1 promoted both cancer cell VEGFC production and cancer cell-induced lymphangiogenesis in colon cancer." (PMID 27145366, 2016). "IRF-2 in exosomes derived from colon cancer lines promotes the proliferation of lymphatic endothelial cells and the formation of the lymphatic network in the sentinel lymph node, increasing the frequency of F4/80+ macrophages and promoting Vascular Endothelial Growth Factor C (VEGFC) secretion." (PMID 31795332, 2019). "Vice versa, colon cancer cells were able to induce secretion of cytokines (TNFα, IL10, IFNγ) and metastasis-related factors (VEGFC, MMPs) in MSC via activation of Wnt signaling which in turn resulted in activation of Wnt pathways in colon cancer cells." (PMID 27608835, 2016). "Noteworthy, an increased expression of FGF-10, VEGFC, IL-10 and TNFα of AMSCs was found to be along with an elevated EMT gene expression of colon cancer cells in the co-culture model in this study." (PMID 26060426, 2015). "Here, we also found a decent increase of VEGFC in AMSCs, suggesting that VEGFC secreted by AMSCs may be in part attributed the increased expression of EMT gene in colon cancer cells." (PMID 26060426, 2015).
glioma (31 papers, 2013 to 2026). A benign or malignant brain and spinal cord tumor that arises from glial cells (astrocytes, oligodendrocytes, ependymal cells). "For instance, the overexpression of Bmi-1 in glioma cells has been linked to increased angiogenesis through the upregulation of vascular endothelial growth factor C (VEGF-C) and NF-κB activation." (PMID 38203185, 2023). "Conversely, prophylactic VEGFC treatment led to near-complete, long-lasting glioma rejection in mice, dependent on drainage to the dCLNs and T cell function." (PMID 38648267, 2024). "Lastly, in addition to immune checkpoint inhibitors, VEGFC also boosted the efficacy of radiation therapy in mouse glioma models via increased drainage of dendritic cells (DCs) from the tumor to the dCLNs." (PMID 38648267, 2024). "When combined with anti-PD1, VEGFC mRNA also conferred long-term resistance to glioma, with T cells from surviving mice providing protection to naïve mice." (PMID 38648267, 2024). "In a companion study, VEGFC messenger RNA (mRNA) was used to improve the efficacy of checkpoint inhibitors in two models of mouse glioma, and the effect was dependent on T cell function." (PMID 38648267, 2024). "Mice injected with glioma cells engineered to overexpress VEGFC showed longer survival and smaller tumor volumes in response to immune checkpoint inhibition compared to mice bearing control gliomas." (PMID 38648267, 2024). "VEGFC is a major driver of lymphangiogenesis, and plays an important role in growth and progression of gliomas." (PMID 34233294, 2021). "In our study, in vivo experiments showed that agomiR-944 injections into xenograft glioma tissues for 3 weeks significantly decreased expression of VEGFC in the glioma tissues." (PMID 34233294, 2021). "Glioma-associated DEGs AKT2, CCL3, STAT2, VEGFC were up-regulated and HIF1A, KRAS, RET, TGFB2 were down-regulated specifically in the dogs." (PMID 29352201, 2018). "Furthermore, the expression of Bmi-1 can activate the NF-κB signaling pathway and increase the expression of vascular endothelial growth factor C (VEGF-C)to promote glioma angiogenesis." (PMID 35897796, 2022). "Furthermore, the GSC-derived exosomal miR-944 dramatically limits glioma angiogenesis by targeting the 3’UTR of VEGFC, reducing VEGFC expression, and blocking the AKT/ERK signaling." (PMID 35663957, 2022). "In this study, our data demonstrated that miR-944 decreased VEGFC expression in glioma cells." (PMID 34233294, 2021). "Moreover, GSC-derived exosomal miR-944 inhibited glioma angiogenesis by downregulating VEGFC and suppressing the activation of the AKT/ERK signaling pathways." (PMID 34233294, 2021). "Notably, the mice with glioma and an overexpression of vascular endothelial growth factor C (VEGF-C) displayed better responses to the anti-tumor therapies, including combinations of the anti- programmed death-1 protein (PD1) and cytotoxic T-lymphocyte-associated protein 4 (CTLA-4) blockade." (PMID 36559105, 2022). "High expression of a common factor initiating angiogenesis, vascular endothelial growth factor-C (VEGF-C), is often correlated to increased vascularity in GLIoma formation." (PMID 33494284, 2021). "Protective genetic changes in glioma include increased expression of ADGRB3/1, IL12B, DYRKA1, VEGFC, LRRC4, and BMP4." (PMID 39022728, 2024). "Improving lymphatic drainage with vascular endothelial growth factor C (VEGF-C), for example, can enhance T cell-based immunotherapy against gliomas." (PMID 35573444, 2022). "In gliomas, CTSB can bind to ANXA2 and induce the expression of vascular endothelial growth factor C, TGF-β, and MMP9 to promote angiogenesis." (PMID 36076905, 2022). "GSC-derived exosomal miR-944 significantly reduced VEGFC levels and suppressed activation of AKT/ERK signaling pathways in HUVECs and xenograft glioma cell tumors." (PMID 34233294, 2021).
glioma (continued). "Presented results indicate that deletion of STAT3 has a significantly suppressive effect on expresison of examined glioma and hypoxia related markers in vitro which could be recapitulated in vivo where, however, this effect is not universal as seen in case of HIF1a and VEGFC expressions." (PMID 38654280, 2024).
esophageal cancer (30 papers, 2003 to 2025). A primary or metastatic malignant neoplasm involving the esophagus. "It is notable that the level of CNTN1 in esophageal cancer cells was associated with vascular endothelial growth factor C (VEGF-C) that induced the recruitment of C/EBPα to interact with CNTN-1 promoter." (PMID 31427725, 2019). "Moreover, in esophageal cancer cells, vascular endothelial growth factor C (VEGF-C) was shown to enhance tumor migration and progression, which was reversed by downregulation of CNTN1." (PMID 29673312, 2018). "In studies on human esophageal cancer, OTUD3 directly interacted with ZFP36 and stabilized the ZFP36 protein by cleaving the K48-type polyUb chain, which subsequently promoted the degradation of vascular endothelial growth factor-C (VEGF-C) mRNA to inhibit lymphatic metastasis." (PMID 41050073, 2025).
glioblastoma (26 papers, 2012 to 2025). The most malignant astrocytic tumor (WHO grade IV). "PV-O glioblastomas were associated with lower expression of VEGFC (p = 0.032) than other periventricular locations, whereas MET overexpression remained exceptional." (PMID 26637806, 2016). "VEGFC mediates glioblastoma survival, tumorigenicity, and bevacizumab resistance via KDR activation." (PMID 40843133, 2025). "In 2020, Song and colleagues published a glioblastoma mouse model receiving “vascular endothelial growth factor C” (VEGF-C) treatment." (PMID 39202398, 2024). "An important experimental finding in this context is the confirmation that lymphocytes migrate from deep cervical lymph nodes into glioblastomas after stimulation with vascular endothelial growth factor-C (VEGF-C), leading to inhibition of tumor progression." (PMID 38275375, 2023). "In this study, we correlated glioblastoma locations with the expression of five mesenchymal genes (VEGFC and its receptor FLT4, HGF and its receptor MET, and CHI3L1) and five proneural genes (PROM1, NOTCH1, DLL3, PDGFRA, and BCAN)." (PMID 26637806, 2016). "Compared to cortical glioblastomas, periventricular glioblastomas were characterized by a higher expression of two mesenchymal genes, VEGFC (p = 0.001) and HGF (p = 0.001)." (PMID 26637806, 2016). "Hence, favoring the development of lymphatic vessels through injection of VEGFC decreased the growth of experimental glioblastoma by enabling immunosurveillance." (PMID 32775327, 2020). "In particular, in contrast with PV-FP and PV-O subtype, PV-T glioblastomas were characterized by a high expression of the mesenchymal marker VEGFC and the proneural and CSC markers NOTCH1 and PROM1 that could be potential targets for specific therapies." (PMID 26637806, 2016). "In glioblastoma (GBM), the Hippo/TAZ axis promotes angiogenesis through the release of vascular endothelial growth factor C." (PMID 39900917, 2025). "VEGFC (p < 0.001), HGF (p = 0.014), and CHI3L1 (p = 0.043) RNA expression levels were significantly different between the five glioblastoma locations." (PMID 26637806, 2016). "In particular, transcriptomic analyses showed a mesenchymal profile for periventricular glioblastoma stem-like cell line, with overexpression of VEGFC and CHI3L1 and a proneural profile for cortical glioblastoma stem-like cell line with overexpression of PROM1, DLL3, and BCAN." (PMID 26637806, 2016).
pancreatic cancer (25 papers, 2006 to 2024). "used of the HDACi B390 to induce apoptosis in pancreatic cancer cells and decreased vascular endothelial growth factor C expression in secreted EVs, inhibiting the nanoparticles role in cancer progression." (PMID 34262674, 2021). "Pathway analysis of its target genes via DAVID showed enrichment (FDR < 5 %) of genes in the Jak-Stat signaling pathway, including several receptors of interleukins (PTPN6, IL22RA1, CREBBP, IL28RA, IL15RA, PIK3R5, STAT3) and pancreatic cancer pathways (VEGFC, ACVR1B, PIK3R5, EGF, STAT3)." (PMID 26572553, 2015). "In pancreatic cancer, infiltration of M2-polarized TAM in regional lymph nodes has the capability of accelerating nodal lymphangiogenesis through the generation of vascular endothelial growth factor C and induction of regional lymph node metastasis." (PMID 31307515, 2019).
esophageal squamous cell carcinoma (23 papers, 2011 to 2024). Esophageal squamous cell carcinoma (ESCC) is a type of esophageal carcinoma (EC) that can affect any part of the esophagus, but is usually located in the upper or middle third. "As to the role of ADAMTS1 in tumor types located on the head and neck, ADAMTS1 was shown to sequester vascular endothelial growth factor C (VEGF-C) and block the lymphangiogenesis and lymphatic metastasis of esophageal SCC." (PMID 38263290, 2024). "Another study showed that increased MMP-1 and vascular endothelial growth factor-C (VEGF-C) expression was associated with an advanced tumor stage and a poor prognosis in patients with esophageal squamous cell carcinoma." (PMID 37513440, 2023). "Moreover, AKIP1 elevates vascular endothelial growth factor-C (VEGF-C) to accelerate angiogenesis and lymphangiogenesis in human esophageal squamous cell carcinoma." (PMID 35965570, 2022).
brain tumors (22 papers, 2020 to 2026). "Here, we show that the MLV-CLN network contributes to RT efficacy in brain tumors and mediates the RT-modulated anti-tumor immunity that is enhanced by vascular endothelial growth factor C (VEGF-C)." (PMID 35301438, 2022). "Furthermore, recent studies have shown that VEGFC‐driven lymphatic drainage of the meninges is critical for modulating depressive behavior and generating effective immune responses against brain tumors." (PMID 41578884, 2026). "Therefore, intracisternal injection of the vascular endothelial growth factor C for stimulation of lymphaneogenesis is proposed as a new promising strategy for the treatment of brain tumors." (PMID 38397864, 2024). "Since CXCL16 was able to activate Akt via inverse signaling mechanisms in brain tumors, the PI3K-AKT signaling pathway might be involved in the regulation of VEGFC expression via CXCL16, and probably via CX3CL1, during cellular dormancy exit." (PMID 32346064, 2020).